RNY1P9 (RNY1 pseudogene 9)
Synonyms: KLHL22-IT1; RNYP1
Gene: Miscellaneous RNA gene on chromosome 22 (20,475,203 to 20,475,311, reverse strand). Ensembl gene ENSG00000255156.
Homologues: Orthologues: chimpanzee Y_RNA (97% identical), macaque Y_RNA (85% identical). Paralogues in human: Y_RNA (80% identical), RNY1 (79% identical), Y_RNA (79% identical), Y_RNA (78% identical), Y_RNA (77% identical), RNY1P2 (76% identical), Y_RNA (76% identical), RNY1P11 (75% identical), Y_RNA (75% identical), RNY1P5 (74% identical), Y_RNA (74% identical), Y_RNA (73% identical), and 88 more.